TREM1 (triggering receptor expressed on myeloid cells 1)
Diseases named in the same sentence as TREM1 in open-access papers (continued):
Sharing a sentence is not in itself a finding about the gene and the disease.
fungal infections (18 papers, 2013 to 2025). "TREM1 was downregulated as well and encodes for proteins associated with monocyte activation after acute bacterial and fungal infections." (PMID 37600779, 2023). "The TREM-1 antagonist peptide inhibits the elevation of inflammatory cytokines caused by fungal infection, whereas blockade of TLR4 enhances the effect of the TREM-1 antagonist peptide." (PMID 36273145, 2022). "TREM-1 is an amplifier of inflammatory and immune responses that functions by mediating cross-talk with TLRs and/or NLRs, which are predominantly associated with bacterial and fungal infection." (PMID 33390769, 2021). "Recent studies on fungal infections have highlighted the critical role of TREM-1, which is highly expressed in infected tissues." (PMID 41226426, 2025). "The triggering receptor expressed on monocytes 1 (Trem1) gene amplifies neutrophil- and monocyte-mediated inflammatory responses triggered by bacterial and fungal infections by stimulating the release of proinflammatory chemokines and cytokines." (PMID 39529886, 2024). "The TREM-1 is expressed on myeloid cell-1 response to bacterial and fungal infections, with its soluble form (sTREM-1) released during human infected tissue." (PMID 35752831, 2022). "In line with its effects on receptor signaling pathways, ibrutinib treatment generally affects neutrophil activation in response to bacterial or fungal infection, which typically engage multiple TLRs, TREM-1 and NLRP3." (PMID 34485307, 2021). "Triggering receptor expressed by myeloid cells (TREM-1) is an amplifier of inflammatory responses triggered by bacterial or fungal infection." (PMID 33390769, 2021). "Research has established that TREM-1 is up-regulated in bacterial, viral and fungal infections, with release of the cell surface portion of the TREM-1 receptor, soluble TREM-1 (sTREM-1) into the blood following activation of the receptor." (PMID 34195785, 2021). "The TREM-1 pathway is known to amplify the inflammatory response in bacterial, viral, and fungal infections, resulting in the release of sTREM-1 into the blood." (PMID 34195785, 2021). "It is possible that fungal infection-triggered TREM-1 signaling activates downstream spleen tyrosine kinase (Syk) and caspase-recruitment domain 9 (CARD9), which is also necessary for Dectin-1 signaling activation." (PMID 26963514, 2016). "In this study, we first demonstrated that the mRNA level of TREM-1 was significantly increased and the majority of infiltrated cells were neutrophils,followed by macrophages in corneas after fungal infection." (PMID 26963514, 2016). "The results indicated that FK506 significantly reduced TREM-1 expression and the release of inflammatory cytokines at an early stage of fungal infection." (PMID 25464008, 2014). "Bacterial or fungal infections can cause up-regulation of membrane bound TREM-1, as well as release in its soluble (s)TREM-1 form rendering it a useful early inflammatory biomarker for systemic infection." (PMID 24124513, 2013). "Additionally, expression of Trem1, which is an amplifier of the inflammatory responses triggered by bacterial and fungal infections, was also increased in the DSS + HF group." (PMID 34795650, 2021). "In addition, activation of Trem1 amplifies monocyte-mediated inflammatory responses/activation triggered by bacterial and fungal infections by stimulating release of pro-inflammatory chemokines and cytokines." (PMID 30779732, 2019). "Simultaneous inhibition of TREM-1 and Dectin-1 showed synergic protection from fungal infection." (PMID 26963514, 2016). "Our data reveal that both TREM-1 and Dectin-1 are significantly enhanced in either human or mouse corneas, which are infiltrated mainly by neutrophils and macrophages after fungal infection, and amplifies corneal inflammation by modulating Th1/Th2 immune responses." (PMID 26963514, 2016).
fungal infections (continued). "We found that FK506 may reduce the infiltration of inflammatory cells by suppressing the expression of proinflammatory cytokines such as TNFα and IL-1β and downregulating the expression of TREM-1 at an early stage of fungal infection in corneas." (PMID 25464008, 2014). "Furthermore, BTK-deficient or ibrutinib/acalabrutinib-treated monocytes and macrophages show defects in TLR-mediated phagocytosis of tumor cells as well as TLR9-, TREM-1 and Dectin-1-dependent production of inflammatory cytokines and phagocytosis upon fungal infection." (PMID 34485307, 2021). "Since both TREM-1 and Dectin-1 (mRNA and protein) expressions were significantly up-regulated in B6 corneas after fungal infection, the next series of in vivo studies were designed to determine whether blockade of TREM-1 and Dectin-1 promotes host resistance to fungal infection." (PMID 26963514, 2016).
pneumonia (18 papers, 2009 to 2025). An acute, acute and chronic, or chronic inflammation focally or diffusely affecting the lung parenchyma, caused by an infection in one or both of the lungs (by bacteria, viruses, fungi, or mycoplasma.). "The role of TREM-1 in viral-associated complications, including pneumonia, is increasingly gaining prominence." (PMID 38515147, 2024). "The influence of a polymorphism (A→T) in exon 2 of the TREM-1 gene was evaluated for association with increased risk of pneumonia by logistic regression analysis." (PMID 24049659, 2013). "This study was undertaken to determine if the TREM-1 SNP (A→T) SNP is associated with the development of pneumonia in burn-injured patients." (PMID 24049659, 2013). "We aimed to evaluate the effect of a functionally relevant TREM-1 single nucleotide polymorphism within the exon 2 (A→T) on the development of pneumonia in burn patients." (PMID 24049659, 2013). "In this study, we found a significant association between the nonsynonymous polymorphism in exon 2 of the TREM-1 gene (T allele) and pneumonia in mechanically ventilated burn patients." (PMID 24049659, 2013). "It was found that TREM-1 expression is significantly increased in lung neutrophils and lung macrophages of patients with pneumonia caused by extracellular bacteria as compared to patients with pulmonary tuberculosis or interstitial lung diseases." (PMID 20011658, 2009). "Similarly, administration of the antagonistic LP17 peptide protected rats from a P. aeruginosa-induced pneumonia, whereas complete deficiency in TREM-1/3 led to markedly increased mortality in Pseudomonas aeruginosa-challenged mice due to defective transepithelial migration of neutrophils." (PMID 24453980, 2014). "Recent evidence suggested that the level of TREM-1 in bronchoalveolar lavage fluid is a potential marker for pneumonia." (PMID 24049659, 2013). "Triggering receptor expressed on myeloid cells-1 (TREM-1) is another biomarker which holds great promise when it comes to pneumonia." (PMID 20011658, 2009). "TREM-1 is selectively expressed in the lungs of patients with pneumonia caused by extracellular bacteria but not in patients with tuberculosis." (PMID 24049659, 2013). "In addition, increased concentrations of TREM-1 in the alveolar compartment have been found in patients with pneumonia and acute lung injury." (PMID 24049659, 2013). "Interestingly, in a murine pneumonia model of Legionella pneumonia no impact of TREM-1 deficiency was found on bacterial clearance or neutrophil influx towards the primary site of infection." (PMID 27253382, 2016). "The double KO Trem-1/3−/− model has elucidated the essential function of TREM-1 in transepithelial neutrophil migration, with significant implications in pneumonia and reproductive tract infections." (PMID 41226426, 2025). "Soluble TREM-1 (sTREM-1), one of the two forms of TREM-1, has been reported as a novel and strong indicator of pneumonia." (PMID 32711473, 2020). "Since it is not feasible to study TREM-1 and TREM-2 mRNA expression at tissue level in these patients, we used our well-established murine model of pneumonia-derived melioidosis in which mice are intranasally infected with a lethal dose of B. pseudomallei." (PMID 27253382, 2016). "Our study has some limitations; we studied a selected group of patients (with symptoms and signs of meningitis or pneumonia), we measured the markers at one time point only, and we did not investigate the membrane-bound components of CD163 or TREM-1." (PMID 19675669, 2009).
Alzheimer disease (17 papers, 2018 to 2025). A progressive, neurodegenerative disease characterized by loss of function and death of nerve cells in several areas of the brain leading to loss of cognitive function such as memory and language. "However, previous studies have already demonstrated the role of TREM-1 in amplifying the inflammatory process and protein autophagy that are associated with tissue damage, as already observed in studies with Parkinson's and Alzheimer's diseases." (PMID 37457576, 2023). "In chronic disorders like Alzheimer’s disease, ongoing TREM-1 activation keeps microglia active and drives neurodegeneration." (PMID 41226426, 2025). "In Alzheimer disease (AD), TREM1 was found to be important for the phagocytosis ability of microglia and therefore lowered the amyloid-β burden in the brain when overexpressed, having a beneficial effect." (PMID 36293468, 2022). "For sterile inflammatory diseases, it was reported that TREM1 played a critical role in the pathogenesis of Alzheimer’s disease because of the potential function in innate immune response and DNA methylation." (PMID 34221733, 2021). "For example, decreased expression of TREM-1 in microglia has been correlated with decreased clearance of Aβ plaques in models of Alzheimer’s disease." (PMID 29391061, 2018). "Notably, our findings align with emerging reports implicating the TREM1-TYROBP complex in Alzheimer’s disease." (PMID 40362275, 2025). "Recent studies indicate that TREM-1 may also play a significant role in various neuroinflammation-related disorders, including subarachnoid hemorrhage, Parkinson’s disease, Alzheimer’s disease and ischemia." (PMID 41226426, 2025). "Recent studies have shown that cerebrospinal fluid (CSF) levels of soluble triggering receptor expressed on myeloid cells 1 (sTREM1) are elevated in individuals with Alzheimer’s disease (AD), though the relationship between CSF sTREM1 and hippocampal atrophy remains to be elucidated." (PMID 39877076, 2024). "As shown by very recent studies, besides IBD, TREM-1 is overexpressed in neurodegenerative disorders, such as Alzheimer’s disease (AD) and ischemia/stroke, where it may contribute to disease pathophysiology." (PMID 31546668, 2019). "TREM1 and TREM2 are better known for their contribution in Alzheimer disease, but in the last couple of years, many investigations have been conducted regarding their contribution to inflammatory processes after SAH." (PMID 36293468, 2022). "The expression of the TREM2 gene, whose product is thought to be protective in Alzheimer’s disease through promotion of amyloid clearance, was down-regulated in SIVE-Meth 3.3-fold, whereas TREM1 gene expression was increased 2.1-fold." (PMID 33198269, 2020).
Hepatic fibrosis (16 papers, 2013 to 2025). The presence of excessive fibrous connective tissue in the liver. "Its close relative, TREM-1, is known to amplify TLR-mediated inflammatory signaling and is strongly implicated in both experimental ALD and human liver fibrosis." (PMID 41497980, 2025). "Studies have demonstrated that silencing the Trem1 gene (Trem1−/−) significantly attenuates liver fibrosis progression." (PMID 41226426, 2025). "Previous studies have primarily focused on the transmembrane form of TREM‐1; we innovatively observed the function of sTREM‐1 as a ligand in liver fibrosis and screened its receptor." (PMID 34750987, 2021). "Heretofore, studies mainly used TREM‐1 as a receptor, but we innovatively utilized sTREM‐1 as a ligand in liver fibrosis to find the receptor that interacts with it." (PMID 34750987, 2021). "So far, scholars have mostly studied the function of TREM‐1 as a receptor, and we pioneered the use of sTREM‐1 as a ligand in liver fibrosis to find receptors that interact with it." (PMID 34750987, 2021). "In the process of hepatic fibrosis, the expression of TREM1 in KCs is significantly increased and inflammatory factors are released." (PMID 33297569, 2020). "The top five functions in HB were TREM1 Signaling and Glucocorticoid Receptor Signaling and in ES they were Hepatic Fibrosis/Hepatic Stellate Cell Activation and Acute Phase Response Signaling." (PMID 24058457, 2013). "The significant canonical pathways based on the overlap percentage and p < 0.05 were coenzyme a biosynthesis, calcium transport I, TREM1 signaling, hepatic fibrosis signaling pathway, and estrogen receptor signaling, with overlap percentages of 66.7%, 40.0%, 13.9%, 7.6%, and 7.6%, respectively." (PMID 38068980, 2023). "Indeed, knockout of TREM-1 (Triggering receptor expressed on myeloid cells), which is highly expressed on KCs in liver fibrosis, reduced liver fibrosis through the inhibition of TNF-α and IL-6 responses in a number of chronic injury models." (PMID 32612603, 2020). "Common features of the top three pathways for KD (Trem1 signaling, Hepatic fibrosis, and IL-10 signaling) and the other groups were the abundance of transcripts related to the activation of the Nlrp3 inflammasome, including Il-1 and caspase-1 related transcripts." (PMID 25614765, 2014). "Of these, Hepatic Fibrosis and TREM1 Signaling are particularly highly correlated." (PMID 24204956, 2013). "Given its fundamental role in fibrosis in complicating HCC pathophysiology, targeting TREM-1 represents a promising therapeutic strategy for managing HCC and liver fibrosis." (PMID 41226426, 2025). "In this review, we evaluate the function of TREM1 and TREM2 in liver injury, NASH, hepatic fibrosis, and HCC." (PMID 33297569, 2020). "Taken together, our data highlighted an important role for the TREM-1-TLR2/4 signaling pathways in regulating M1 macrophage polarization in CDAHFD-fed induced NASH and liver fibrosis, indicating that inhibition of TREM-1 signaling might be an effective therapeutic target for NASH and liver fibrosis." (PMID 32195263, 2020).
glioblastoma (15 papers, 2009 to 2025). The most malignant astrocytic tumor (WHO grade IV). "In glioblastoma, a hypoxia-inducible inflammatory gene signature inclusive of myeloid-derived TREM1 and IL8 expression was significantly associated with poorer overall survival of patients." (PMID 34956864, 2021). "While these findings establish TREM1’s oncogenic functions, its precise mechanisms in glioma-associated macrophages-particularly regarding immunosuppression and proneural-to-mesenchymal transition in glioblastoma-require further investigation." (PMID 41394801, 2025). "TREM1 expression in the tumor-associated Mφ (TAMs) from primary and recurrent glioblastomas obtained from the Brain Immune glioblastoma Atlas portal confirms an increase in the TREM1-positive subsets of TAMs from 21.3% in the primary glioblastoma to 36.8% in the recurrent glioblastoma." (PMID 36249290, 2022). "Thus, prevention of HuR dimerization leads to downregulation of the TREM1+-glioblastoma microenvironment and is associated with a reduction in cell fusion events between tumor and myeloid-derived cells in the mouse glioblastoma model." (PMID 36249290, 2022). "The OS results indicated that TREM1 is a risk factor for patients with glioblastoma multiforme (GBM), kidney renal clear cell carcinoma (KIRC), lower grade glioma (LGG), liver hepatocellular carcinoma (LICH), mesothelioma (MESO), pancreatic adenocarcinoma (PAAD) and stomach adenocarcinoma (STAD)." (PMID 39744496, 2025). "In cohorts of patients with liver hepatocellular carcinoma (LIHC) and glioblastoma multiform (GBM), high TREM1 expression was associated with worse overall survival and positively correlated with immune trafficking and myeloid cell recruitment." (PMID 37651197, 2023). "Spatial transcriptomic analysis of glioblastoma of different molecular subtypes confirmed an accumulation of TREM1 and other myeloid-cell markers in the peri-necrotic zones enriched with highly mutagenic tumor cells." (PMID 36249290, 2022). "Nevertheless, we found that transcriptome status was altered in macrophages between primary and recurrent glioblastoma, including TREM1 signaling, NFAT activity, CCR5 signaling, and phospholipase C signaling." (PMID 35203505, 2022). "In this report, we demonstrate a positive correlation between cell fusion events in glioblastoma and the TREM1+-myeloid-derived microenvironment." (PMID 36249290, 2022). "In agreement with recent scientific reports, we confirmed that TREM1 is highly expressed in glioblastomas of all molecular subtypes." (PMID 36249290, 2022). "In mouse glioblastoma models, we demonstrated a reduction in the TREM1+-microenvironment and glioblastoma/host cell fusion after treatment with SRI42127." (PMID 36249290, 2022). "TREM1 signaling was differentially identified in radioresistant and high PD-L1-expressing glioblastoma tumors in the TCGA glioblastoma population." (PMID 35203505, 2022). "The in vitro upregulation of TREM1 in macrophages triggered the release of colony-stimulating factor-1 (CSF-1), triggering invasive activity and pathologic angiogenesis in glioblastoma cells." (PMID 35203505, 2022). "This effort provides a detailed characterization of the myeloid-derived TREM1+-glioblastoma microenvironment." (PMID 36249290, 2022). "The ability of an inhibitor of HuR dimerization SRI42127 to suppress TREM1+-microenvironment and glioblastoma/myeloid-derived cell interaction was assessed in vivo and in vitro." (PMID 36249290, 2022). "An increase of TREM1 was confirmed in the peri-necrotic areas of all glioblastoma molecular subtypes." (PMID 36249290, 2022). "TREM1+-myeloid-derived microenvironment promulgates glioblastoma heterogeneity and is a therapeutic target." (PMID 36249290, 2022). "This manuscript outlines a novel axis directly involved in cell fusion events and promulgating glioblastoma progression, the TREM1+-HuR-dependent myeloid-derived glioblastoma microenvironment." (PMID 36249290, 2022).